CDC42 (cell division cycle 42)
Diseases named in the same sentence as CDC42 in open-access papers (continued):
Sharing a sentence is not in itself a finding about the gene and the disease.
intestinal cancer (1 paper, 2016). "There are no mutations reported in the Cdc42 itself, but inhibition of Cdc42 leads to regression of tumors in intestinal cancers which harbour mutations in APC/β-Catenin, but there is no direct evidence for its involvement in CSC maintenance." (PMID 27597870, 2016).
intracerebral hemorrhage (1 paper, 2025). A cerebrovascular disorder characterized by bleeding into one or both cerebral hemispheres including the basal ganglia and the cerebral cortex. "Importantly, Astragaloside IV likely prevents the proliferation and migration of microglia/macrophages after intracerebral hemorrhage (ICH) by binding its transformed products to CDC42, PTK2, and CSF1R in C57 BL/6 mice model." (PMID 41049135, 2025).
intrauterine growth restriction (1 paper, 2021). "During intrauterine growth restriction, Rac1 and Cdc42 were positively correlated with mTOR." (PMID 34221974, 2021).
irritable bowel syndrome (1 paper, 2025). Irritable bowel syndrome (IBS) is a chronic functional condition of the lower gastrointestinal (GI) tract characterized by abdominal pain or discomfort and disordered bowel habit (diarrhea, constipation, or fluctuation between the two). "Notably, irritable bowel syndrome (IBS) has been linked to mutations in SCN5A and variations in CDC42 and NXP1, with higher concordance observed among monozygotic twins." (PMID 41416253, 2025).
ischemia (1 paper, 2021). A hypoperfusion of the BLOOD through an organ or tissue caused by a PATHOLOGIC CONSTRICTION or obstruction of its BLOOD VESSELS, or an absence of BLOOD CIRCULATION. "Moreover, recent studies have reported that downregulation of miR-137 inhibits oxidative stress-induced cardiomyocytes apoptosis by targeting the KLF15 gene and protects cells against ischemia-induced apoptosis through CDC42." (PMID 33670982, 2021).
Klebsiella pneumoniae (1 paper, 2024). "Here the authors characterise a cell division cycle 42 (CDC42)-165aa protein encoded by circRNA circCDC42 that promotes Pyrin-inflammasome mediated pyroptosis in Klebsiella pneumoniae (KP) infection and inhibition of circCDC42 reduces KP induced lung injury in mice." (PMID 38977695, 2024).
laryngeal carcinoma (1 paper, 2025). Carcinoma that arises from the laryngeal epithelium. "Key genes like CDC42, PXN, ITGB1, PGK1, SLC2A1, ISG15 and ICAM1, affected by HPV, display distinct functional alterations and complex correlations in laryngeal cancer progression." (PMID 40821990, 2025).
Legionella infection (1 paper, 2015). "To determine if caspase-1 is required for the dephosphorylation of cofilin in response to Legionella infection by halting the activity of kinases or promoting the activity of phosphatases that converge on cofilin, we first assessed Rac1 and Cdc42 activation." (PMID 26686473, 2015).
leukocytosis (1 paper, 2025). "In comparison to the CDC42 group, they had less leukocytosis (p < 0.001), and normal counts of neutrophils (p = 0.04) and B cells (p = 0.02)." (PMID 40860338, 2025).
Lyme disease (1 paper, 2025). Lyme disease (named after the towns in the USA where the disease was first identified) is a bacterial infection caused by Borrelia burgdorferi. "However, no orthologs of these factors exist in B. burgdorferi, which suggests that the use of Cdc42 and Rac1 by the Lyme disease spirochete occurs through a previously undescribed mechanism." (PMID 39727396, 2025).
lymphocytic neoplasm (1 paper, 2021). "However, low stringency functional analysis revealed predicted inhibition of lymphocytic neoplasm (65 genes, p = 3.6 × 10−3, Z score = −2.2) and activation of the Cdc42 (cell division cycle 42) signaling pathway (9 genes, p = 4.2 × 10−4, Z score = 2.2) as unique to heterozygous females." (PMID 34210092, 2021).
malignant renal cell carcinoma (1 paper, 2022). "In addition, CUL2, CDC42, GLUT1 and other proteins, which have been demonstrated to be critical in malignant renal cell carcinoma, were predicted to be downstream target proteins of microRNAs differentially expressed in PMAH patients compared with normal controls." (PMID 34986816, 2022).
medulloblastoma (1 paper, 2022). A malignant, invasive embryonal neoplasm arising from the cerebellum. "Specifically, CDC42 has been shown to act as a regulator of medulloblastoma-associated genes and compounds for its inhibition have also been proposed." (PMID 35213534, 2022). "Furthermore, CDC42, which has been proposed as a candidate target for medulloblastoma, plays a role in several cancers." (PMID 35213534, 2022).
meningioma (1 paper, 2024). A generally slow growing tumor attached to the dura mater. "Loss of TRAF7 in meningeal cells promoted the activity of CDC42 and the p21-activated kinase PAK1 and enhanced RAS activity and the upregulation of the MAPK cascade in meningioma cells, suggesting that these pathways might be important in TRAF7-mutated meningiomas." (PMID 38571886, 2024).
metastasis (1 paper, 2026). The spread or migration of cancer cells from one part of the body (where they first appeared) to another. "High Cdc42 expression was significantly associated with Kirsten rat sarcoma viral oncogene homolog (KRAS) wild-type status (p = 0.001), lymph node metastasis (p = 0.039), and perineural invasion (p = 0.021)." (PMID 42194810, 2026).
metastatic prostate carcinoma (1 paper, 2020). A carcinoma that arises from the prostate gland and has spread to other anatomic sites. "ZCL278 is another selective Cdc42 small-molecule inhibitor that blocks the binding of Cdc42 to intersectin, thereby suppressing actin-based motility and migration in metastatic prostate cancer cells." (PMID 32392742, 2020).
multiple sclerosis (1 paper, 2022). A progressive autoimmune disorder affecting the central nervous system resulting in demyelination. "In the “inhibition of remyelination in multiple sclerosis: regulation of cytoskeleton proteins”, MAPT—in which Fyn suppression inactivates the guanine nucleotide exchange factor Vav 2 via CDC42—destabilizes the actin microfilaments." (PMID 35804531, 2022).
muscle tumors (1 paper, 2021). "Rac1 and Cdc42 are involved in myoblast transformation, and they play an important role in muscle tumors." (PMID 34221974, 2021).
myopia (1 paper, 2019). "CDC42, a GTPase directly downstream of LINC00339, contained three significant variants in the two-point analysis, but has not previously been implicated in myopia either." (PMID 30704416, 2019).
nail infection (1 paper, 2024). An infectious process affecting the nail. "To elucidate the effect of the Cdc42/Rac inhibitor against T. rubrum nail infection, we tested EHop-016 in an in vitro T. rubrum nail infection model." (PMID 38952678, 2024).
nephrosis (1 paper, 2018). Pathological processes of the KIDNEY without inflammatory or neoplastic components. "To test whether loss of function of ITSN1 and ITSN2 GEF activity causes a nephrosis phenotype in humans, we examined the effect of mutations identified in patients with pTSNS on the active states of Cdc42." (PMID 29773874, 2018).
neurodevelopmental disability (1 paper, 2023). "In addition to Cdc42, de novo mutations in Atp2b1 are thought to cause a monogenic form of neurodevelopmental disability, according to genetic discoveries, the probands’ overlapping phenotypes, and functional investigations." (PMID 36975497, 2023).
nonallergic rhinitis (1 paper, 2010). "Two of these genes, c-fos and cell division cycle 42 (cdc42) were found to have pivotal roles in the possible mechanistic pathways of nonallergic rhinitis and the authors believe these genes could be potentially useful as biomarkers for this condition and aid in diagnosis." (PMID 20465792, 2010).
oropharyngeal squamous cell carcinoma (1 paper, 2025). "In the context of recurrent or metastatic oropharyngeal squamous cell carcinoma (OSCC, a form of HNSCC), CDC42 partakes in the pathologic and progressive aspects of the disease by modulating malignant tumor behavior and immune evasion (Chen, Chen & Liu, 2024)." (PMID 40821990, 2025).
otitis media (1 paper, 2021). Inflammation of the anatomical structures of the middle ear, which is most often caused by an infectious process. "CDC42 (ENSP00000314458) is an immune system-associated gene; we found that it was closely associated with otitis media." (PMID 34912812, 2021).
ovarian endometriosis (1 paper, 2022). A non-neoplastic disorder characterized by the growth of endometrial tissue in the ovaries. "Expression of CDC42 was previously investigated using immunostaining of eutopic and ectopic endometrium in 19 patients with ovarian endometriosis with some weak evidence of increased expression in secretory phase endometrium in those with disease." (PMID 35514537, 2022).
papillary adenocarcinoma (1 paper, 2008). A morphologic variant of adenocarcinoma. "In contrast, those promoting Ca++ desensitization, such as the MLCPs (Ppm1a, Ppm1g, Pp2r2d, Ppp2r1a, Ppp1 catalytic subunit and Cdc42), were more highly expressed in the papillary adenocarcinoma tumors." (PMID 18811984, 2008). "Interestingly, Cdc42 and its downstream N-WASP, which induces filopodia, were highly expressed in the papillary adenocarcinomas." (PMID 18811984, 2008).
papillary thyroid carcinoma (1 paper, 2016). "Interestingly, a recent study reported srGAP1 as a candidate susceptibility gene in papillary thyroid carcinoma, and several mutations of srGAP1 identified in papillary thyroid carcinoma resulted in severely impaired ability of srGAP1 to inactivate CDC42." (PMID 27923383, 2016).
pheochromocytoma (1 paper, 2020). "In this study, we further showed that the inhibition of Rac1 and Cdc42 activities in human pheochromocytomas was directly correlated to reduced expression of the GEFs ARHGEF1 and FARP1, respectively." (PMID 32664294, 2020). "For example, in pheochromocytoma, a NET arising from chromaffin cells of the adrenal medulla, we observed that the activity of Rac1 and Cdc42 was inhibited while their relative expression remained unchanged compared to non-tumor tissue." (PMID 32664294, 2020).
polyp (1 paper, 2023). A usually exophytic mass attached to the underlying tissue by a broad base or a thin stalk. "Our study found that CDC42 expression was significantly increased in high-risk polyp tissues, whereas its expression in COAD tissues was reduced compared to high-risk polyps." (PMID 37365287, 2023). "In conclusion, our study identified an association between the increased expression of CDC42, TAGLN, and GSN in high-risk polyps, suggesting a potential role in polyp malignancy." (PMID 37365287, 2023).
premature ovarian failure (1 paper, 2022). "Previous studies showed that miR-23a promotes cell apoptosis in hGCs via the FasL-Fas, ERK1/2, and CDC42/PAK1 signaling pathways, which are related to ovarian reserve function and premature ovarian failure." (PMID 35740072, 2022).
psychosis (1 paper, 2014). "In addition to the changes caused by olanzapine in methylation in psychosis-related canonical pathways, the results showed decreased methylation of genes involved in CDC42 and calcium signalling (P = 2.5 × 10–3) in the hippocampus." (PMID 24382160, 2014).
pulmonary sarcoidosis (1 paper, 2020). Sarcoidosis affecting the lung parenchyma. "In the overlapping canonical pathways analysis of BALF proteins in progressive and non-progressive cases, CD28, CDC-42 and IL-8 signaling, and Th1 pathways had high-connectivity suggesting a central role of these pathways in the progression of pulmonary sarcoidosis." (PMID 32764642, 2020).
retinoblastoma (1 paper, 2013). A malignant tumor that originates in the nuclear layer of the retina. "In retinoblastoma it was found that Cdc42 reactivity, measured by immunohistochemistry and Western blotting, had no prognostic value, and that over-expression of Cdc42 did not correlate with tumour invasion or histological differentiation." (PMID 23420497, 2013).
serous ovarian cancer (1 paper, 2020). "CDC42 was identified as one of the important mediators of compressive stimulation-led mechanotransduction in high grade serous ovarian cancers." (PMID 32532057, 2020). "Significant CDC42 upregulation was observed in both high grade serous ovarian cancer cell types and compressive stimulation conditions (static and cyclic) compared to non-stimulated 3D controls." (PMID 32532057, 2020). "Dual treatment with CDC42 inhibitor along with combination chemotherapies, increases high grade serous ovarian cancer cell death, while reducing proliferation." (PMID 32532057, 2020).
systemic candidiasis (1 paper, 2019). "Additionally, Ras1 activation of cAMP synthesis leads to maintenance of the hyphal growth, a virulence factor in systemic candidiasis, by regulating the G1 cyclin Hgc1 which binds to Cdc28 to localize Cdc42 to the hyphal tip." (PMID 31825988, 2019).
systemic sclerosis (1 paper, 2011). A chronic disorder, possibly autoimmune, marked by excessive production of collagen which results in hardening and thickening of body tissues. "It was demonstrated in systemic sclerosis microvascular ECs (SSc MVECs) that full length uPAR is required for cdc42- and Rac-mediated cytoskeletal organization." (PMID 21535874, 2011).
T-cell immunodeficiency (1 paper, 2023). A broad classification of disorders that affect the cell-mediated aspect of the immune response. "This is also the first report associating an N-terminal CDC42 variant with severe T cell immunodeficiency, mimicking the one encountered in T-B + SCID." (PMID 37581646, 2023).
Tangier disease (1 paper, 2018). "Fibroblasts in Tangier disease display decreased expression and activity of Cdc42, which controls cytoskeletal architecture and vesicular transport." (PMID 30425683, 2018).
tongue tumors (1 paper, 2022). "In our HPV16-E6/E7 transgenic mouse model of tongue tumors, we found that tumor lesions in the tongue were much smaller in the inhibitor-treated and siRNA-treated groups compared with the DEPC-treated group, which might be due to decreased Cdc42 expression and increased E-cad expression." (PMID 36077689, 2022).
Type 2 diabetic nephropathy (1 paper, 2022). "Type 2 diabetic nephropathy mouse models were established to identify the expression of Cdc42 in podocytes by immunohistochemistry." (PMID 36034435, 2022).
Wilms tumor (1 paper, 2019). An embryonal neoplasm characterized by the presence of epithelial, mesenchymal, and blastema components. "In fact, a recent report has shown that Wilms tumor gene on the X chromosome (WTX)—a putative tumor suppressor gene—inhibits CDC42 activation through binding to RhoGDI2 and then stabilizing the complex formation of RhoGDI1 and CDC42." (PMID 31492019, 2019).
Yersinia pseudotuberculosis infection (1 paper, 2012). "Other publications however indicate that upon Yersinia pseudotuberculosis infection YopT cleaves RhoA as well as Rac and Cdc42 from nascent phagosomes and affects RhoG." (PMID 22792400, 2012).
cancer (411 papers, 2005 to 2026). A tumor composed of atypical neoplastic, often pleomorphic cells that invade other tissues. "Rac-1 and Cdc42 are known to be over-expressed in several cancers and is associated with poor prognosis and drug resistance." (PMID 37024613, 2023). "CDC42 family GTPases (RHOJ, RHOQ, CDC42) are linked to multiple human cancers and modulate cell-cycle progression, tumor cell migration/invasion, and tumor angiogenesis." (PMID 35385746, 2022). "CDC42 is a member of the Rho family of GTPase signalling molecules, and its overexpression in some cancers has been implicated in increased cell migration." (PMID 35514537, 2022). "Overexpression or loss of Cdc42 also contributes to the development of some benign diseases through the same or similar signaling pathways as malignant tumors, such as insulin secretion, insulin resistance, airway inflammation and neurodegenerative diseases." (PMID 35154449, 2022). "The overexpression of CDC42 is associated with poor prognosis in BC because CDC42 enhances the migration of cancer cells." (PMID 36077333, 2022). "In cancer, CDC42 activation has been commonly associated with oncogenic traits such as increased cell migration and invasion." (PMID 36369429, 2022). "In fibroblasts, CDC42 activation contributes to tumor promoting activity of cancer-associated fibroblasts (CAFs), and impacts on matrix remodelling or angiogenesis." (PMID 33406731, 2021). "The expression levels of three gene targets correlated with the risk scores, demonstrating that elevated hTERT, Rac1, and Cdc42 levels are associated with cancer recurrence and poor prognosis." (PMID 33510789, 2021). "For the 28 potential Cdc42 GEFs, amplification and mutation are the most frequently reported types of alteration across all cancer types." (PMID 34196668, 2021). "Unlike Ras, which is activated primarily by point mutations that impair its GTPase activity in human cancers, Cdc42 is activated by changes in upstream regulators." (PMID 34804913, 2021). "Cdc42 is a small GTPase which is implicated in the progression of cancer via regulation of many cellular processes." (PMID 33536006, 2021). "Mutations in Cdc42 itself are rarely found in cancers, however alterations to its regulators have been extensively characterized with many GEFs identified as oncogenes and some GAPs as tumour suppressors." (PMID 34100887, 2021). "The Rho family protein Cdc42 is weakly transforming in its own right but essential for transformation by Ras, the most highly mutated oncogene found in human cancer." (PMID 34100887, 2021). "Based on the signaling outcomes from Rac1 or Cdc42 activation, overexpression of each protein has been implicated in cancer growth, progression and metastasis, chemoresistance, and for some tumors, poor patient outcomes." (PMID 33413202, 2021). "The Cdc42 kinase effectors PAK1, PAK2, PAK4, MRCKα, MRCKβ and ACK have all been directly targeted, consistent with cancer mutational data indicating that these proteins show the highest incidence of alterations amongst the Cdc42 effectors." (PMID 34100887, 2021). "Overexpression of P29S mutation after UV exposure is reportedly involved in cancer proliferation and migration through Cdc42 and Rac1." (PMID 34201921, 2021). "Recent studies have identified activating mutations in Rho GTPases, such as RhoA, Rac1, and Cdc42, in various human cancers." (PMID 32392742, 2020). "Cdc42 has been found in multiple human cancers and is implicated in tumor growth, cell-cycle progression, epithelial-mesenchymal transition, angiogenesis, oncogenic transformation, and tumor migration/invasion." (PMID 32843668, 2020). "Cell division cycle 42 (CDC42) is implicated in cell cycle progress, migration, invasion, growth and angiogenesis in multiple human cancers." (PMID 31889909, 2019).